CD47 (CD47 molecule)
Diseases named in the same sentence as CD47 in open-access papers (continued):
Sharing a sentence is not in itself a finding about the gene and the disease.
gastric cancer (33 papers, 2015 to 2025). A primary or metastatic malignant neoplasm involving the stomach. "In summary, our research has validated the elevated expression of CD47 in human gastric cancer and its significant association with unfavorable prognosis." (PMID 38532108, 2024). "Clinical investigations have revealed an association between high CD47 expression in ovarian and gastric cancer cells and unfavorable prognosis." (PMID 39594611, 2024). "In this study, we have substantiated the high expression of CD47 in gastric cancer tissues, establishing a strong association with unfavorable prognosis." (PMID 38532108, 2024). "The findings of our investigation substantiated the overexpression of CD47 in gastric cancer, establishing a significant association with unfavorable prognosis." (PMID 38532108, 2024). "This is in accordance with a previous study in gastric cancer, where CD47 expression was linked with a lower CD8/FOXP3 ratio." (PMID 35406573, 2022). "In studies of Epstein-Barr virus-associated gastric carcinoma (EBVaGC), CD47 expression was increased in EBVaGC tissue samples compared to EBV-negative gastric cancer tissue samples." (PMID 32082311, 2020). "Furthermore, analysis of gene expression data from the GEPIA database supports the positive association between VEGF and CD47 in gastric cancer tissues." (PMID 38532108, 2024). "However, little is known regarding the expression of CD47, which may be associated with tumor progression in gastric cancer." (PMID 26077800, 2015). "Before examining the impact of targeting the CD47/SIRPα axis, we utilized CD47+ gastric cancer patient-derived cells (PDC1 and PDC2) and verified their identity through flow cytometry analysis." (PMID 38532108, 2024). "Our preclinical studies collectively offer substantiation that CD47 holds promise as a prospective target for gastric cancer, while also highlighting the potential of anti-angiogenic therapy to enhance tumor responsiveness to anti-CD47 immunotherapy." (PMID 38532108, 2024). "In this context, a comprehensive analysis was conducted on a cohort of 89 patients diagnosed with gastric cancer, to elucidate the clinical relevance of CD47 in the context of gastric cancer." (PMID 38532108, 2024). "Nevertheless, the efficacy of CD47 as a viable therapeutic target for gastric cancer remains uncertain owing to contradictory outcomes reported in prior research." (PMID 38532108, 2024). "The utilization of SIRPα-Fc in anti-CD47 therapy has demonstrated remarkable efficacy in Hu-PDX models of gastric cancer." (PMID 38532108, 2024). "In our study, we observed a significant presence of microvessels in gastric cancer following anti-CD47 treatment, leading us to discover that tumor angiogenesis plays a crucial role in limiting the effectiveness of anti-CD47 therapy for the first time." (PMID 38532108, 2024). "The expression of CD47 in clinical gastric cancer tissues was assessed using immunohistochemistry and Western blot." (PMID 38532108, 2024). "For gastric cancer, CD47 protein expression was observed in 57 of 115 patients and served as an independent adverse prognostic factor." (PMID 39594611, 2024). "In this study, clinical specimens were obtained from a cohort of 89 patients diagnosed with gastric cancer, and subsequent analysis was conducted to assess the expression of CD47 in both tumor tissues and corresponding normal tissues." (PMID 38532108, 2024). "Overall, we demonstrated that tumor-derived exosomes are involved in GCLM progression, targeting CD47 inhibits gastric cancer tumorigenesis, and a combination of anti-CD47 antibodies and 5-Fu shows potential for treating GCLM." (PMID 36860925, 2023). "We report here on the antitumour efficacy with blockade upregulating CD47 expression in the tumour microenvironment and conferring gastric cancer resistance to antiangiogenic therapy." (PMID 35694254, 2022).
gastric cancer (continued). "We designed in vitro macrophage migration and phagocytosis assays to evaluate the efficacy of anti-CD47 mAb alone or with bevacizumab as a therapeutic in gastric cancer, especially for preventing early seeding events." (PMID 35694254, 2022). "Here, we report a synergistic antitumour strategy through simultaneous blockade of VEGF and CD47 signalling to enhance the curative effect of advanced gastric cancer." (PMID 35694254, 2022). "First, mechanism by which HIF and CD47 axis became activated on gastric cancer cells relapsing from anti-angiogenic therapy is quite preliminary." (PMID 35694254, 2022). "CD47 has been reported to be frequently up-regulated in multiple kinds of cancers, such as ovarian cancer, gastric cancer, breast cancer and NSCLC." (PMID 32314789, 2020). "Future studies should continue to attempt to elucidate the respective role(s) of CD47 in different cancer types including pancreatic and gastric cancer." (PMID 32082311, 2020). "In this study, we investigated the expression of CD47 in gastric cancer in clinical and experimental settings, and we elucidated the therapeutic potential of targeting CD47 for treating gastric cancer." (PMID 26077800, 2015). "In this study, we demonstrated that patients with highly expressed CD47 in gastric cancer tissue had unfavorable outcomes and that CD47 expression on gastric cancer cells was an independent prognostic factor." (PMID 26077800, 2015). "In this study, we demonstrated that a blocking antibody directed against CD47 preferentially enabled the phagocytosis of gastric cancer cells by human macrophages as well as murine macrophages." (PMID 26077800, 2015). "In conclusion, CD47 is an adverse prognostic factor and promising therapeutic target in gastric cancer." (PMID 26077800, 2015). "We also showed that a CD47 blocking antibody enhanced the phagocytosis of gastric cancer cells by macrophages and significantly improved the survival rate in an intraperitoneal cancer dissemination model." (PMID 26077800, 2015). "In conclusion, both CD44 and CD47 were highly expressed in gastric cancer cells, and their higher expressions correlated with higher proliferation and tumorigenicity in vitro and in vivo." (PMID 26077800, 2015). "Our study has shown that CD47 serves as a viable therapeutic target for gastric cancer, and it has also presented a potentially effective combination approach involving the inhibition of both the CD47/SIRPα axis and angiogenesis for the treatment of this disease." (PMID 38532108, 2024). "However, the clinical significance of CD47 expression in gastric cancer and the efficacy of targeting CD47 as a strategy for eradicating tumor cells have yet to be fully understood." (PMID 38532108, 2024). "Additionally, there exists a positive correlation between VEGF expression and CD47 expression in gastric cancer." (PMID 38532108, 2024). "To accurately and authentically forecast the efficacy of anti-CD47 immunotherapy on human gastric cancer, we developed Hu-PDX models that maintained the attributes of the original tumors and provided a more accurate representation of the pertinent constituents and interactions within the TME." (PMID 38532108, 2024). "Nevertheless, the clinical relevance of CD47 in gastric cancer and its potential as a therapeutic target remains unclear." (PMID 38532108, 2024). "Subsequently, an investigation was conducted to determine whether the inhibition of VEGF could augment the effectiveness of CD47 blockade in gastric cancer." (PMID 38532108, 2024). "In light of the ongoing debate surrounding CD47 expression in gastric cancer, our study sought to assess the expression of CD47 in tumor tissues and their corresponding adjacent mucosae from a cohort of 89 gastric cancer patients." (PMID 38532108, 2024).
gastric cancer (continued). "Furthermore, we proceeded to investigate the therapeutic potential of anti-CD47 treatment in gastric cancer, revealing that the blockade of CD47 effectively impeded tumor growth by activating macrophage-mediated innate and adaptive immune responses." (PMID 38532108, 2024). "In addition, an examination was conducted on the relationship between VEGF and CD47 in gastric cancer." (PMID 38532108, 2024). "In gastric cancer, high CD47 expression has been shown to indicate a poor prognosis." (PMID 36860925, 2023). "By immunization alpacas with recombinant human CD47, we prepared a CD47-targeting nanobody C2 and developed [68Ga]Ga-NOTA-C2, followed by an exploration of the diagnostic value in CD47-expressing tumor models including gastric-cancer patient-derived xenograft models." (PMID 36939440, 2023). "Besides, in gastric carcinoma, abnormal CD47 expression is a standalone indicator of adverse survival outcomes and fluorouracil-based adjuvant chemotherapy resistance." (PMID 37719086, 2023). "Our results from the flow cytometry analyses and transwell array showed that Bevacizumab significantly decreased the macrophage infiltration compared to controls; however, inhibiting CD47 reversed macrophage infiltration to gastric cancer cells, which was reduced by antiangiogenic therapy." (PMID 35694254, 2022). "Therefore, targeting CD47 should be a promising and fruitful therapeutic approach for treating gastric cancer." (PMID 26077800, 2015). "In this regard, CD47-targeted therapy may be advantageous for clinical applications to treat gastric cancer as a CSC-based therapy." (PMID 26077800, 2015). "A more detailed understanding of the modulation of CD47 could open new avenues for CSC-based immunotherapy for treating gastric cancer." (PMID 26077800, 2015). "Notably, an analysis of samples obtained from patients with gastric cancer using immunohistochemistry revealed a novel finding: VEGF levels were significantly elevated in samples exhibiting high CD47 expression compared to those with low CD47 levels." (PMID 38532108, 2024). "Notably, our study also revealed a positive correlation between VEGF expression and CD47 in gastric cancer tissues, suggesting the potential efficacy of combining anti-CD47 and anti-angiogenesis therapies for the treatment of gastric cancer in clinical settings." (PMID 38532108, 2024). "However, the relationship between ARID1A and CD47 expression and their prognostic value in gastric cancer (GC) are still unknown." (PMID 34805154, 2021). "Humanized patient-derived xenografts (Hu-PDXs) models were established to assess the efficacy of anti-CD47 immunotherapy or the combination of anti-CD47 and anti-VEGF therapy in treating gastric cancer." (PMID 38532108, 2024). "It is noteworthy that anti-CD47 immunotherapy has been observed to sustain tumor angiogenic vasculature, with a positive correlation between the expression of VEGF and CD47 in gastric cancer." (PMID 38532108, 2024). "Accumulating evidence showed a positive connection between high CD47 expression and poor prognoses in various cancers, such as NSCLC and gastric cancer (GC)." (PMID 37138855, 2023). "After treatment of gastric cancer xenograft models, the bevacizumab group exhibited upregulation of HIF-1 and CD47 mRNA." (PMID 35694254, 2022). "Our in vitro results confirmed that THBS2 knockdown inhibited CD47 and MMP-2 expression and the progression of pancreatic and gastric cancers." (PMID 35701829, 2022). "MKN45 and MKN74 gastric cancer cells were sorted by fluorescence-activated cell sorting according to CD44 and CD47 expression levels, and their in vitro proliferation, spheroid-forming capacity, and in vivo tumorigenicity were studied." (PMID 26077800, 2015). "Flow cytometric analyses revealed that the MKN45 and MKN74 gastric cancer cell lines expressed both CD44 and CD47 on ∼90% of the tumor cells." (PMID 26077800, 2015).
gastric cancer (continued). "Expression of CD47 and CD44, a known gastric cancer stem cell marker, were investigated in gastric cancer cell lines by flow cytometry." (PMID 26077800, 2015). "We performed xenograft transplantations of FACS-sorted gastric cancer cells according to the CD44 and CD47 expression levels of the MKN45 and MKN74 cancer cell lines into the subcutaneous space of SCID mice." (PMID 26077800, 2015). "We evaluated the proliferation of gastric cancer cells according to the expression levels of CD44 and CD47, that is, CD44hi or CD44lo and CD47hi or CD47lo." (PMID 26077800, 2015). "The results of this study indicate that the combination of CD47 and VEGF blockade may be a viable approach for treating gastric cancer." (PMID 38532108, 2024). "Immunohistochemical staining of both normal mucosae and tumor tissues revealed a significant upregulation of CD47 in gastric cancer tissues, irrespective of their differentiation stage." (PMID 38532108, 2024). "On the basis of the flow cytometry and IHC scouting results, we selected SKOV-3, LS174T, and a PDX (No. 490 gastric cancer) models with relatively high CD47 expression for the experiments." (PMID 36939440, 2023). "Furthermore, blockade of CD47 and VEGF by specific Abs inhibited spontaneous pulmonary metastasis of BGC-823 gastric cancer cells in vivo." (PMID 35694254, 2022). "In fibrolamellar hepatocellular carcinoma and gastric cancer, higher CD47 expression has not been seen." (PMID 33765961, 2021). "In our study, ∼90% of the MKN45 and MKN47 gastric cancer cells highly co-expressed CD44 and CD47." (PMID 26077800, 2015). "In contrast, an alternative investigation has revealed no statistically substantial variation in CD47 mRNA levels between primary gastric cancer and healthy tissues, thereby concluding that CD47 in primary gastric tumors does not exhibit any correlation with clinicopathological factors or prognosis." (PMID 38532108, 2024). "However, the mechanism by which CD47 is upregulated in gastric cancer cells relapsing after antiangiogenic therapy is not clear." (PMID 35694254, 2022). "Moreover, in gastric carcinoma, no overexpression of CD47 was found when compared to adjacent non-tumor gastric tissue." (PMID 33765961, 2021). "However, CD47 expression in gastric cancer is not well documented." (PMID 26077800, 2015). "Similarly, the other gastric cancer cell lines, such as MKN7, KATOIII, and NUGC3, expressed both CD44 and CD47 with different fluorescence intensities (data not shown)." (PMID 26077800, 2015).
acute lymphoblastic leukemia (30 papers, 2015 to 2026). Leukemia with an acute onset, characterized by the presence of lymphoblasts in the bone marrow and the peripheral blood. "Knocking out QPCTL suppressed tumor growth via disrupting monocyte homeostasis, and knocking out QPCTL together with blocking immune checkpoint CD47 has been verified to improve the killing of T-acute lymphoblastic leukemia cells." (PMID 37063864, 2023). "MicroRNA 708 was directly targeted CD47 and resulted in downregulation of CD47 on T cell acute lymphoblastic leukemia cell line." (PMID 35418166, 2022). "Human acute lymphoblastic leukemia (ALL) patient samples showed 2-fold higher CD47 expression compared to normal bone marrow, and higher CD47 level independently correlated with worse overall survival." (PMID 34584838, 2021). "After the approval of blinatumomab, a bispecific antibody (bsAb) targeting on CD19 for acute lymphoblastic leukemia, a few of CD47-targeted bsAbs for cancer immunotherapy, are currently in clinical research." (PMID 34305918, 2021). "Specifically, binding of miR-708 to two sites in the CD47 3′UTR was capable of reducing CD47 levels in T cell acute lymphoblastic leukemia." (PMID 32722019, 2020). "Expression of CD47 is regulated by a variety of factors such as Myc oncogene that stimulate expression of CD47 gene, which has been studied in models of T cell acute lymphoblastic leukemia (T-ALL) and in oral squamous cell carcinoma (OSCC)." (PMID 38892394, 2024). "CD47 also appears to have an important role in several hematological malignancies, such as acute lymphoblastic leukemia (ALL) and AML." (PMID 35433462, 2022). "Parallel experiments using cells from human acute lymphoblastic leukemia (ALL) patients showed similar inhibition of leukemia formation by the anti‐CD47 antibody." (PMID 32281289, 2020). "Finally, the blockade of CD47 with miR-708 produced phagocytosis and promoted apoptosis in a human CCRF-CEM leukemic T cell line and in human T-acute lymphoblastic leukemia Jurkat cells after transfection with miR-708 mimic." (PMID 38339019, 2024). "The anti-CD47/CD19 BsAb TG-1801 (NI-1701) has demonstrated strong potential in preclinical studies to elicit ADCP and ADCC in malignant B-cell lines and primary tumor B-cells from patients with acute lymphoblastic leukemia (ALL), chronic lymphocytic leukemia (CLL), and several subtypes of NHL." (PMID 39040441, 2024).
diffuse large B-cell lymphoma (26 papers, 2017 to 2026). "CD47 blockade enhances antitumor responses through trogocytosis in renal cell carcinoma and diffuse large B-cell lymphoma." (PMID 41417432, 2025). "The CD47 blocker TTI-621 is evaluated with anti-PD-1 antibody pembrolizumab in diffuse large B-cell lymphoma." (PMID 41417432, 2025). "A recent result indicated that the expression of CD47 is downregulated by berberine in diffuse large B-cell lymphoma at the transcriptional level via suppressing c-myc expression." (PMID 36144625, 2022). "Berberine, according to Ren and colleagues, has antitumor activity in diffuse large B-cell lymphoma by modulating the c-myc/CD47 axis." (PMID 36144625, 2022). "The suppression of CD47 enhances the phagocytosis of macrophages, which contributes to eliminate diffuse large B-cell lymphoma cells both in vitro and in vivo." (PMID 35046810, 2021). "Berberine is beneficial in immunochemotherapy based on rituximab in combination with anti-CD47 in diffuse large B-cell lymphoma." (PMID 35046810, 2021). "Berberine exerts antitumor activity in diffuse large B-cell lymphoma, a subtype of non-Hodgkin lymphoma by modulating the c-myc/CD47 axis." (PMID 35046810, 2021). "Interestingly, CD24 acts as a complementary signal of CD47 and appears to have inversely correlated expression in human diffuse large B‐cell lymphoma." (PMID 33449453, 2021). "Grouping patient samples based on CD47 mRNA expression levels, investigators showed improved overall survival in patients with CD47 low tumors, especially diffuse large B cell lymphoma (DLBCL), B cell chronic lymphocytic leukemia, and mantle cell lymphoma subsets." (PMID 34944850, 2021). "Conversely, CD24 expression did not correlate with survival in diffuse large B-cell lymphoma (DLBCL), whereas CD47 did." (PMID 35625912, 2022). "CD47 is variably expressed in many subsets of B-cell NHL including diffuse large B-cell lymphoma (DLBCL), chronic lymphocytic leukemia (CLL), follicular lymphoma (FL), mantle cell lymphoma (MCL), and marginal zone lymphoma (MZL)." (PMID 32677994, 2020). "A xenograft model of canine diffuse large B-cell lymphoma was sensitive to combinatorial anti-CD20 and CD47 blockade therapy." (PMID 37090720, 2023). "Furthermore, BBR performs anti-tumor roles in diffuse large B cell lymphoma (DLBCL) related to rituximab-based immunochemotherapy and CD47-targeted immunotherapy." (PMID 36561763, 2022). "Contrarily, in diffuse large B-cell lymphoma (DLBCL), CD24 mAb treatment was less successful than CD47 mAb treatment." (PMID 38279998, 2024). "Treatment of diffuse large B‐cell lymphoma (DLBCL) and mantle cell lymphoma (MCL) cell lines with 9‐cis‐retinoic acid (RA) and IFN‐α was found to exert therapeutic effects through the induction of CRT outgrowth, early HSP70/90 membrane exposure, CD47 downregulation, and enhanced HMGB1 secretion." (PMID 36815385, 2023). "Therefore, it is expected that this mechanism will result in a negative correlation between SIRPα-CD47 axis expression and survival as it was described, for example, for follicular lymphoma, diffuse large B-cell lymphoma, and esophageal squamous cell carcinoma." (PMID 37291116, 2023).